SMC5 (structural maintenance of chromosomes 5)
Description:
Core component of the SMC5-SMC6 complex, a complex involved in repair of DNA double-strand breaks by homologous recombination. The complex may promote sister chromatid homologous recombination by recruiting the SMC1-SMC3 cohesin complex to double-strand breaks. The complex is required for telomere maintenance via recombination in ALT (alternative lengthening of telomeres) cell lines and mediates sumoylation of shelterin complex (telosome) components which is proposed to lead to shelterin complex disassembly in ALT-associated PML bodies (APBs). Required for recruitment of telomeres to PML nuclear bodies. Required for sister chromatid cohesion during prometaphase and mitotic progression; the function seems to be independent of SMC6. SMC5-SMC6 complex may prevent transcription of episomal DNA, such as circular viral DNA genome.
Synonyms: KIAA0594; SMC5L1; ATELS2
Tractability: PROTAC: UniProt records ubiquitination sites on it; ubiquitination databases record sites on it; its protein half-life has been measured.
Gene: Protein-coding gene on chromosome 9 (70,258,270 to 70,354,874, forward strand). Ensembl gene ENSG00000198887.
Subcellular location: Nucleus; Chromosome; Nucleus, PML body; Chromosome, telomere
Subcellular location (Human Protein Atlas): Nuclear speckles
Pathways (Reactome):
Metabolism of proteins: SUMOylation of DNA damage response and repair proteins
Gene Ontology:
Molecular function: DNA secondary structure binding; protein binding; single-stranded DNA binding; ATP hydrolysis activity
Biological process: cellular senescence; DNA damage response; double-strand break repair via homologous recombination; double-strand break repair via nonhomologous end joining; host-mediated suppression of viral genome replication; positive regulation of chromosome segregation; positive regulation of maintenance of mitotic sister chromatid cohesion; telomere maintenance via recombination; chromatin looping; protein sumoylation; regulation of telomere maintenance; chromosome organization; double-strand break repair
Cellular component: chromosome, telomeric region; interchromatin granule; nuclear speck; nucleus; PML body; site of double-strand break; Smc5-Smc6 complex; chromosome; nucleoplasm; sex chromosome
Genetic constraint (gnomAD): Loss-of-function variants: 60 observed, 103.87 expected, observed/expected ratio (o/e) 0.58, 90% interval 0.47 to 0.72. The upper end of that interval is the gene's LOEUF score, 0.72, which puts it in group 2 of 6, group 1 being the genes least tolerant of losing a copy. Missense variants: 888 observed, 1,033.5 expected, observed/expected ratio (o/e) 0.86, 90% interval 0.81 to 0.91. Synonymous variants: 333 observed, 348.58 expected, observed/expected ratio (o/e) 0.96, 90% interval 0.87 to 1.05.
Homologues: Orthologues: guinea pig SMC5 (91% identical), mouse Smc5 (89% identical), tropical clawed frog smc5 (65% identical), zebrafish pimr7 (38% identical), Drosophila melanogaster SMC5 (27% identical), Caenorhabditis elegans smc-5 (26% identical). Paralogues in human: SMC6 (17% identical).
Diseases named in the same sentence as SMC5 in open-access papers:
SMC5 is named in the same sentence as 50 diseases in open-access papers, as found by Europe PMC text mining. Sharing a sentence is not in itself a finding about the gene and the disease. The quoted sentences say what the papers report.
microcephaly (5 papers, 2020 to 2024). A congenital or acquired developmental disorder in which the circumference of the head is smaller than normal for the person's age and sex. "The first identified patient with cardiac disease carried a variant in NSMCE2, a component of the SMC5/6 complex, which causes primordial dwarfism with microcephaly." (PMID 38203602, 2023). "The three known SMC complexes (SMC1/3, SMC2/4, and SMC5/6) function in diverse roles in DNA replication and repair, but all have been associated with microcephaly due to abnormal neurodevelopment." (PMID 38203602, 2023). "Further work with Smc5 cKO in the CNS shows that defects in brain growth with loss of SMC5 are secondary to DNA bridges and chromosomal missegregation in neural progenitor cells, subsequently leading to brain microcephaly and reduced cortical size." (PMID 38203602, 2023). "Collectively, these clinical and genetic observations support the premise that variants in SLF2 and SMC5 cause microcephaly and short stature associated with cardiac defects and the development of anemia." (PMID 36333305, 2022). "Here, the authors identify mutations in SLF2 and SMC5 as cause of Atelís Syndrome characterized by microcephaly, short stature, anemia, segmented chromosomes and mosaic variegated hyperploidy." (PMID 36333305, 2022). "Mutations of SMC5/6 components cause developmental defects, including primary microcephaly." (PMID 33200984, 2020). "Prior work on the SMC5/6 complex demonstrates increased DNA damage in the mouse brain in a Smc5K371del knock-in mouse model, as well as microcephaly and increased apoptosis in the zebrafish brain with smc5 KO." (PMID 38203602, 2023). "A recent report of 11 patients with variants in SMC5 and SLF2 (SMC5-SMC6 complex localization factor 2) displayed microcephaly, anemia, short stature, and cardiac defects." (PMID 38203602, 2023). "In vivo ablation of slf2 and smc5 in zebrafish recapitulate patient phenotypes including microcephaly and craniofacial patterning defects, likely due to concomitant cell cycle defects and apoptosis." (PMID 36333305, 2022). "Here, we identify biallelic variants in two components of the RAD18-SLF1/2-SMC5/6 genome stability pathway, SLF2 and SMC5, in 11 patients with microcephaly, short stature, cardiac abnormalities and anemia." (PMID 36333305, 2022). "However, we demonstrate that conditional KO (cKO) of Smc5 restricted to the central nervous system (CNS) in mice induces microcephaly and affects several neural functional networks as measured by functional magnetic resonance imaging (fMRI)." (PMID 38203602, 2023). "Smc5 KO zebrafish showed microcephaly, short length and disturbed glucose metabolism." (PMID 36627765, 2023). "By querying gene matching platforms, four patients exhibiting microcephaly and growth retardation that had undergone WES were identified to carry biallelic variants in SMC5: patient P7 (c.1110_1112del; p.Arg372del, c.1273C>T; p.Arg425Ter) and patients P8, P9-1 and P9-2 (c.2970C>G; p.His990Asp)." (PMID 36333305, 2022). "Here we report the clinical and genetic characterization of 11 patients with biallelic variants in two components of the newly described RAD18-SLF1/2-SMC5/6 DDR pathway, SLF2 and SMC5, exhibiting microcephaly, short stature, cardiac defects and anemia." (PMID 36333305, 2022). "In summary, we demonstrate that loss of SMC5 in the developing embryo produces CHD and NDD through independent processes and that microcephaly occurs with and without concurrent CHD." (PMID 38203602, 2023).
Atelís Syndrome (4 papers, 2022 to 2025). "Biallelic variants in SMC5, a core component of the DNA repair machinery, cause Atelis Syndrome, characterized by severe growth failure and multi-system abnormalities." (PMID 41374403, 2025). "In addition to reduced brain size, NDD, and CHD, patients with variants in SLF2 or SMC5 were found to have ocular abnormalities, growth restriction, anemia, and skin hyperpigmentation, a condition recently named Atelis syndrome." (PMID 38203602, 2023). "However, in examining the phenotype of Atelis syndrome patients with SMC5 variants, while NDD and cardiac phenotypes are common, the other signs such as eye defects, skin hyperpigmentation, or anemia are not present in all patients." (PMID 38203602, 2023). "As a core component of this pathway, SMC5 has recently been implicated in the etiology of MVA syndrome, specifically Atelis syndrome." (PMID 41374403, 2025).
hepatocellular carcinoma (4 papers, 2017 to 2024). A malignant tumor that arises from hepatocytes. "A study using clinical samples has shown that the anti-Smc5/6 function can be retained in HBx variants found in patients with hepatocellular carcinoma (HCC)." (PMID 39339838, 2024). "Expressing DDB1 in hepatoma cells restores HBx-mediated SMC5/6 degradation and enhances cccDNA transcriptional activity." (PMID 38757942, 2024). "The different behavior of HepG2-NTCP cells in response to HBV infection suggested that the abundance and the regulation of Smc5/6 complex in hepatoma cell lines had been altered." (PMID 34370796, 2021). "This suggests that the Smc5/6-involved DNA damage repair mechanism may be significantly changed in hepatoma cell lines such as HepG2." (PMID 34370796, 2021). "We also discuss what is known regarding the repression of cccDNA transcription by Smc5/6, the timing of HBx expression, and the potential role of HBx in promoting hepatocellular carcinoma (HCC)." (PMID 28368357, 2017).
lung disease (3 papers, 2016 to 2022). "Thus, it is noteworthy that mutations in SMC complexes are implicated in human diseases, e.g., mutations in the cohesin complex subunits can lead to Cornelia syndrome or mutations in the Nse3 subunit of Smc5/6 causes the lung disease chromosome breakage immunodeficiency syndrome (LICS)." (PMID 35052348, 2021).
viral infection (3 papers, 2022 to 2024). "SMC5/6 may act as intrinsic immunosensors and restriction factors of human herpes virus RC in viral infectious diseases." (PMID 37007526, 2023). "However, it has been demonstrated that even in the absence of viral infection and HBx protein, SMC5/6 interacts with CRL4, and its levels show a dependence on CRL activity." (PMID 38256025, 2024). "However, the interaction of SMC5/6 with CRL4 and the CSN also occurs in the endogenous cellular context, in the absence of viral infection." (PMID 38256025, 2024).
Bloom syndrome (2 papers, 2015 to 2020). Bloom syndrome (BSyn) is a rare chromosomal breakage syndrome characterized by a marked genetic instability associated with pre- and postnatal growth retardation, facial sun-sensitive telangiectatic erythema, increased susceptibility to infections, and predisposition to cancer. "In this context, Smc5/6 is crucial to compensate for deficiencies in the RecQ helicase Sgs1/BLM, mutated in cancer-prone Bloom syndrome patients, likely by its role in modulating resolution or remodeling of the emerging recombination intermediates." (PMID 26698660, 2015). "Furthermore, him-6 mutants, defective for the C. elegans orthologue of the BLM (Bloom syndrome) helicase, and smc-6 mutants, defective for the Smc5/6 cohesin-like complex, showed an increased incidence of SVs." (PMID 32358516, 2020).
breast carcinoma (2 papers, 2020 to 2021). "The result showed that U50A consistently downregulates SMC5, ATRX, CENPE, and CENPF, indicating a widespread phenomenon that these genes are downstream targets of U50A in breast cancer." (PMID 34944924, 2021).
developmental delays (2 papers, 2018 to 2023). "Furthermore, Smc5 cKO alters brain FC and may predispose patients to increased developmental delays." (PMID 38203602, 2023).
Fanconi anemia (2 papers, 2020 to 2022). Fanconi anemia (FA) is a hereditary DNA repair disorder characterized by progressive pancytopenia with bone marrow failure, variable congenital malformations and predisposition to develop hematological or solid tumors. "Here, we report 11 patients with a neurodevelopmental disorder overlapping clinically with MVA and Fanconi Anemia (FA) with pathogenic variants in SLF2 and SMC5, two components of the recently discovered RAD18-SLF1/2-SMC5/6 genome stability pathway." (PMID 36333305, 2022). "The structural maintenance complex SMC5/6 interacts with and functions jointly with key components of the Fanconi anemia pathway to facilitate DNA repair and preserve genome stability." (PMID 31867888, 2020). "Here, we show that SMC5 dysfunction in avian DT40 B cells causes mitotic delay and hypersensitivity toward DNA intra‐ and inter‐strand crosslinkers (ICLs), with smc5 mutants being epistatic to FANCC and FANCM mutations affecting the Fanconi anemia (FA) pathway." (PMID 31867888, 2020).
hepatitis B (2 papers, 2020 to 2022). "Additionally, SMC5/6 has been shown to associate with hepatitis B and herpes simplex-1 viral episomes." (PMID 32992873, 2020). "It is known that a host Smc5/6 (chromosomes 5/6 complex) restricts HBV (Hepatitis B virus) infection by inhibiting HBV genome transcription." (PMID 35053283, 2022).
Insulin resistance (2 papers, 2023 to 2024). Increased resistance towards insulin, that is, diminished effectiveness of insulin in reducing blood glucose levels. "In‐frame Arg372 deletion of SMC5 gene causes dwarfism, diabetes and extreme insulin resistance." (PMID 36627765, 2023). "We identified a homozygous in‐frame deletion of Arg372 in SMC5, one of the core subunits of the SMC5/6 complex, from an adult patient with microcephalic primordial dwarfism, chromosomal instability and insulin resistance." (PMID 36627765, 2023). "In summary, we identified a homozygous in‐frame deletion of Arg372 in the SMC5 gene as the cause of a syndrome of MPD, diabetes and extreme insulin resistance." (PMID 36627765, 2023). "Our study demonstrates the association between homozygous in‐frame deletion of Arg372 in SMC5 and a syndrome characterized by primordial dwarfism, extreme insulin resistance and diabetes." (PMID 36627765, 2023). "For example, SMC5/6-destabilizing mutations in NSMCE3 cause lung disease-immunodeficiency-chromosomal breakage syndrome (LICS), and NSMCE2 or SMC5 mutations result in primordial dwarfism and insulin resistance." (PMID 38886582, 2024). "However, the potential link between defects in the SMC5/6 complex and insulin resistance remains unclear." (PMID 36627765, 2023).
aortic valve stenosis (1 paper, 2023). Aortic valve stenosis (AVS) is a condition characterized by narrowing of the heart's aortic valve opening. "The proband in our study presented with the most complex cardiac anatomy associated with variants in SMC5, namely severe mitral stenosis, aortic valve stenosis, ascending aorta hypoplasia, severely diminished left ventricular size, and partial anomalous pulmonary venous return." (PMID 38203602, 2023).
atherosclerosis (1 paper, 2024). A disease characterized by the build-up of fatty material and calcium deposition in the arterial wall resulting in partial or complete occlusion of the arterial lumen. "Given prominent significance of SMC5 in atherosclerosis progression, we put focus on it for further exploration." (PMID 38389849, 2024). "By high throughput RNA sequencing, loss-of-function experiment and SMC-lineage tracing technology, we identified SMC as the origin of SMC5 and demonstrated a regulating role of IRF8 in SMC transdifferentiation towards macrophage during atherosclerosis." (PMID 38389849, 2024).
atrial septal defect (1 paper, 2023). Interauricular communication is a congenital malformation characterized by a communication between the atrial chambers of the heart. "Additional work has described patients with variants in SMC5 and a variety of non-cyanotic cardiac defects, including persistent ductus arteriosus, atrial septal defect, or supravalvular pulmonic stenosis." (PMID 38203602, 2023).
cecum adenocarcinoma (1 paper, 2023). "The mRNA level of SMC5 was significantly downregulated in CRC (colon adenocarcinoma (COAD), rectal adenocarcinoma (READ), cecum adenocarcinoma (CEAD), and restosigmoid adenocarcinoma (RESAD)) compared to the normal tissues (colon and rectum) based on sample types and individual cancer stages." (PMID 35894836, 2023).
Cognitive impairment (1 paper, 2023). Abnormal cognition is characterized by deficits in thinking, reasoning, or remembering. "In summary, the changes in brain volume observed for the Smc5 cKO, can result in functional connectivity differences, which can lead to cognitive impairments and motor sensory anomalies, the latter of which we previously confirmed for this model." (PMID 38203602, 2023).
female subfertility (1 paper, 2016). "Furthermore, Smc5/6-deficient flies displayed female subfertility, which was shown by reduced hatch rates of smc5/6 eggs." (PMID 27288507, 2016). "Smc5/6 exhibited a maternally contributed function in maintaining chromosome stability during early embryo development, which manifested as female subfertility in its absence." (PMID 27288507, 2016).
hyperglycaemia (1 paper, 2023). "Unexpectedly, qPCR showed reduced expression of G6PC, PCK1, FBP1 with the down‐regulation of SMC5, suggesting that hepatic gluconeogenesis is not the cause of hyperglycaemia." (PMID 36627765, 2023).
hypoplastic left heart syndrome (1 paper, 2023). Hypoplastic left heart syndrome (HLHS) refers to the abnormal development of the left-sided cardiac structures, resulting in obstruction to blood flow from the left ventricular outflow tract. "A patient with hypoplastic left heart syndrome and gross motor delay presented with a de novo mutation in SMC5." (PMID 38203602, 2023). "Here, we report the association of a variant in SMC5 with hypoplastic left heart syndrome, the first association of SMC5 with a cyanotic heart lesion." (PMID 38203602, 2023).
latent infection (1 paper, 2022). "The reduction of H3K27ac on the RTA promoter by SMC6 promotes the repression of RTA during latency, indicating that SMC5/6 may play an important role in maintaining latent infection." (PMID 35914008, 2022).
lentivirus infection (1 paper, 2023). Virus diseases caused by the Lentivirus genus. "Interfering with the expression of Smc5 led to severe defect in adipogenesis, which was observed when the lentivirus infection occurred 4 days before differentiation (D − 4)." (PMID 36627765, 2023).
leukemia (1 paper, 2024). A malignant (clonal) hematologic disorder, involving hematopoietic stem cells and characterized by the presence of primitive or atypical myeloid or lymphoid cells in the bone marrow and the blood. "In K562 (myeloid) and Jurkat (T-cell) leukemia cells, shRNA was used to constitutively deplete SMC5." (PMID 38886582, 2024).
malignant fibrous histiocytoma (1 paper, 2020). "In the Detwiller datasets, SMC5 was overexpressed in synovial sarcoma (3.206-fold) and malignant fibrous histiocytoma (3.228-fold) compared to normal samples." (PMID 33460400, 2020).
microcephalic primordial dwarfism (1 paper, 2022). Primordial dwarfism with microcephaly. "All SLF2 and SMC5 mutant LCLs examined exhibited a significant increase in spontaneous replication fork stalling and fork asymmetry comparable to that observed in an LCL derived from an ATR-Seckel Syndrome patient." (PMID 36333305, 2022).
osteosarcoma (1 paper, 2016). A usually aggressive malignant bone-forming mesenchymal neoplasm, predominantly affecting adolescents and young adults. "By using a commonly used human osteosarcoma cell line (U2OS), we extended our knowledge regarding the roles of SMC5/6 in human genome integrity maintenance." (PMID 27792189, 2016). "By using a human osteosarcoma cell line (U2OS), we show that after the CRISPR-Cas9-mediated removal of the SMC5/6 subunit NSMCE2, treatment with the topoisomerase II inhibitor etoposide triggered an increased sensitivity in cells lacking NSMCE2." (PMID 27792189, 2016).